DNM1 (dynamin 1)
Diseases named in the same sentence as DNM1 in open-access papers (continued):
Sharing a sentence is not in itself a finding about the gene and the disease.
Epileptic encephalopathy (continued). "We present evidence that heterozygous DNM1‐related developmental and epileptic encephalopathy shows a progressive cone‐rod synaptic retinal dysfunction in childhood." (PMID 39925045, 2025). "We therefore reveal a preclinical model and potential therapy that will provide impetus to future small molecule screening studies and clinical trials to generate interventions for DNM1 epileptic encephalopathy." (PMID 37648685, 2023). "BMS-204352 is therefore a promising lead compound for future trials in DNM1 epileptic encephalopathy." (PMID 37648685, 2023). "In summary, these results suggest that BMS-204352 has high potential for therapy in DNM1 epileptic encephalopathy, since it corrects dysfunction at the cellular, circuit and behavioural level in a preclinical model of this disorder." (PMID 37648685, 2023). "In order to make the distinction for DNM1 epileptic encephalopathy, we engineered a conditional Dnm1Ftfl mouse model of DNM1 EE." (PMID 26125563, 2015). "Therefore, the Dnm1+/R237W mouse has both construct and face validity as a preclinical model of DNM1 epileptic encephalopathy." (PMID 37648685, 2023). "All patients with DNM1 mutation-related epileptic encephalopathy were nonverbal except for two patients, which were not mentioned in literature, with severe to profound intellectual disability." (PMID 31920647, 2019). "Thus far, the specific clinical and electroencephalographic features of children with DNM1 mutation-related epileptic encephalopathy have not been clearly established." (PMID 31920647, 2019). "Thus far, the full clinical and electroencephalographic features of children with DNM1 mutation-related epileptic encephalopathy have not been established." (PMID 31920647, 2019).
infantile spasms (9 papers, 2015 to 2023). A rare epilepsy syndrome characterized by onset of epileptic spasms in infants between 2 and 12 months of age, and rarely up to 24 months. "In general, disease-causing DNM1 variants are responsible for around 2% of patients with infantile spasms or the Lennox–Gastaut syndrome." (PMID 37900685, 2023). "De novo mutations in dynamin-1 (DNM1) cause a severe DEE with both infantile spasms (IS) and LGS, that is highly resistant to current ASMs." (PMID 35250833, 2022). "To date, it has been clarified that DNM1 pathogenic variants can be associated with Lennox-Gastaut syndrome and infantile spasms." (PMID 35350397, 2022). "Among these, variants in the DNM1 gene have emerged as definitive causes of DEEs, including infantile spasms and Lennox–Gastaut syndrome." (PMID 33372033, 2021). "Children with pathologic DNM1 variants have severe seizures and experience cognitive decline, typically presenting with infantile spasms that progress to Lennox–Gastaut syndrome." (PMID 33372033, 2021). "We show that patients with DNM1 mutations have a phenotype characterized by intellectual disability, hypotonia, and refractory epilepsy typically presenting with infantile spasms." (PMID 28667181, 2017). "Recently, mutations in DNM1 (dynamin 1) have been implicated in two EE syndromes, Lennox-Gastaut Syndrome and Infantile Spasms." (PMID 26125563, 2015). "Recently, de novo missense mutations in DNM1 have been implicated in two EE’s, Lennox-Gastaut Syndrome and Infantile Spasms." (PMID 26125563, 2015). "Patients carrying DNM1 mutations may present with infantile spasms in more than a half of the cases, usually associated with axial and/or diffuse hypotonia with severe impairment of motor skills." (PMID 35350397, 2022). "DNM1 encodes a brain-specific GTPase, dynamin-1, which mediates presynaptic endocytosis, and the few individuals identified with pathogenic DNM1 variants suffer from developmental and epileptic encephalopathy syndromes including Lennox-Gastaut syndrome and infantile spasms." (PMID 34690692, 2021). "Patients having disease-causing variants in the DNM1 gene typically reveal profound hypotonia from birth, infantile spasms that might lead to the Lennox–Gastaut syndrome, developmental delay, microcephaly (few patients), cortical visual impairment, speech delay, and intellectual disability." (PMID 37900685, 2023). "DNM1 (dynamin 1): The common phenotype includes severe-to-profound ID, hypotonia and frequent (76%) EE characterized by infantile spasms, frequently evolving into Lennox–Gastaut syndrome and drug resistance." (PMID 33919646, 2021). "These mutations have been reported in association with early onset epileptic encephalopathy, intractable seizures (seizure onset in DNM1 patients ranges from 2–13 months of and usually presents with infantile spasms." (PMID 31920647, 2019). "DNM1 patients have seizures that begin early in life and usually manifest as infantile spasms." (PMID 26125563, 2015).
Intellectual disability (7 papers, 2017 to 2025). "Heterozygous pathogenic variants in DNM1 result in Developmental and Epileptic Encephalopathy type 31A, where patients exhibit early onset refractory epilepsy, severe‐profound intellectual disability and poor visual behaviour." (PMID 39925045, 2025).
developmental delay (5 papers, 2015 to 2023). "Herein, we describe a proband having pathogenic Class-I variant in the DNM1 that revealed neurodevelopmental features such as developmental delay, moderate–severe ID, microcephaly, hypotonia, seizures, and speech issues." (PMID 37900685, 2023). "Here, we present the third homozygous variant in DNM1 in a female who presented with global developmental delay, myoclonic seizures, facial dysmorphism, and nystagmus." (PMID 36553519, 2022). "Pathogenic DNM1 gene variant presents with developmental delay and neurologic disorders." (PMID 36203798, 2022).
Encephalopathy (5 papers, 2015 to 2024). Encephalopathy is a term that means brain disease, damage, or malfunction. "In conclusion, to the best of our knowledge, this is the first integrated analysis of the phenotypic, genetic, and electroencephalographic features of children with DNM1 mutation-related encephalopathy." (PMID 31920647, 2019). "The relatively homogeneous phenotype and the predicted dominant-negative mechanism of this mutation make DNM1 encephalopathy an interesting therapeutic target for pharmacologic approaches and gene therapy to restore DNM1 function." (PMID 28667181, 2017). "DNM1 encephalopathy is a disease of vesicle fission, and the mutations in our patient cohort cluster in 2 major functional domains of the DNM1 protein: the GTPase domain and the middle domain." (PMID 28667181, 2017). "However, missense mutations associated with DNM1 encephalopathy are clustered within either the GTPase domain or the middle domain, which, along with the GTPase effector domain (GED), is required for oligomerization and stimulation of GTPase activity." (PMID 32844156, 2020). "Our study highlighted the role of series EEG and video EEG of children with DNM1 mutation-related encephalopathy; EEG patterns may aid in providing clues for treatment." (PMID 31920647, 2019). "For the analysis of DNM1-related encephalopathy, 31 out of the 33 patients were included (9 females, 21 males, the sex of one patient was not available)." (PMID 31920647, 2019). "We delineate the phenotypic spectrum of DNM1 encephalopathy, an emerging disease of synaptic vesicle fission." (PMID 28667181, 2017). "The phenotypic spectrum of DNM1-related encephalopathy is relatively homogeneous, in contrast to many other genetic epilepsies." (PMID 28667181, 2017). "The relatively homogeneous phenotype and predicted dominant-negative mechanism of this mutation make DNM1-associated encephalopathy has the potential of being an effective therapeutic target." (PMID 31920647, 2019). "Here, we aim to characterize the phenotypic and genetic spectrum of DNM1 encephalopathy." (PMID 28667181, 2017). "However, we speculate that underlying neural network abnormalities were ameliorated by immunological mechanisms caused by the viral infection rather than by a specific immune response to DNM1 encephalopathy." (PMID 38903324, 2024).
glioma (5 papers, 2013 to 2025). A benign or malignant brain and spinal cord tumor that arises from glial cells (astrocytes, oligodendrocytes, ependymal cells). "Possibly, early-stage gliomas upregulate DNM1 to support synaptic-like vesicle recycling, then transition to DNM2-mediated uptake in intermediate stages." (PMID 40705199, 2025). "In this study, we found that heparan sulfate proteoglycan 2 (perlecan) (HSPG2), syndecan-1 (SCD1), clathrin (CLTC), and dynamin (DNM1) were present in all patient-derived glioma cells." (PMID 36992317, 2023). "In our control using a neuronal-specific gene we demonstrated that glioma cells express the Dnm1 gene and that its expression is affected by RSV, even in acute treatments." (PMID 28441400, 2017). "Analysis by RT-qPCR of some of the selected genes in a glioma cell line showed that dynamin 1 mRNA was down-regulated even in acute trans-resveratrol treatments." (PMID 28441400, 2017). "Dynamin-1 can compensate the dynamin-2 inhibition as dynamin-1 is known being typically expressed in neurons, neuroendocrins cells and also in glioma cells." (PMID 24386117, 2013).
Alzheimer disease (4 papers, 2012 to 2022). A progressive, neurodegenerative disease characterized by loss of function and death of nerve cells in several areas of the brain leading to loss of cognitive function such as memory and language. "In the AppNL-F knockin mouse model of Alzheimer’s disease, increased turnover resulted from imbalances in both synthesis and degradation, converging on proteins associated with synaptic vesicle recycling (Dnm1, Cltc, Rims1) and mitochondria (Fis1, Ndufv1)." (PMID 34979241, 2022). "In addition, dynamin 1 expression is significantly decreased in an animal model of Alzheimer’s disease." (PMID 33352833, 2020). "Furthermore, treatment of these rats with memantine, a classic NMDA antagonist used to treat Alzheimer's disease, resulted in decreased dynamin 1 degradation and increased memory ability." (PMID 22536397, 2012).
developmental and epileptic encephalopathy (4 papers, 2021 to 2025). An epilepsy associated with developmental impairment that may be due to either the underlying etiology or the superimposed epileptic activity, or both. "Recurrent DNM1 de novo splice-site variant has also been associated with developmental and epileptic encephalopathy with a dominant-negative mechanism." (PMID 37900685, 2023). "The present study characterizes how the expression of a dominant-negative variant of Dnm1, a gene associated with developmental epileptic encephalopathies, affects excitatory and inhibitory synapses in cultured cortical neurons." (PMID 33372033, 2021). "Recent work has identified genetic variants in DNM1 as among the more common causes of developmental epileptic encephalopathies (DEEs), but the physiological consequences of its mutation are unclear." (PMID 33372033, 2021). "In this study, we presented another autosomal recessive case caused by a novel deleterious homozygous loss-of-function variant in DNM1 and provided detailed clinical, neuroradiological, and molecular results of a patient who presented with developmental and epileptic encephalopathy." (PMID 36553519, 2022).
breast carcinoma (3 papers, 2019 to 2024). "We previously reported a greater downregulation in DNM1 levels in plasma extracellular vesicles (EVs) proteomes of breast cancer survivors with perceived cognitive impairment." (PMID 39516074, 2024). "Following that, a syngeneic young-adult WT (C57BL/6) female mouse model of breast cancer chemobrain was developed to study DNM1 expression in the hippocampus." (PMID 39516074, 2024). "In total, breast cancer-bearing mice treated with adjuvant ADR-CYP showed the most drastic reductions in the DNM1 immunoreactivity in the hippocampal CA1 and CA3 subregions important for learning and memory functions." (PMID 39516074, 2024). "Thus, increased expression of Dnm1 and decreased expression of PUMA may contribute to breast cancer susceptibility." (PMID 32942660, 2020). "We found the most drastic reductions in DNM1 immunoreactivity within hippocampal CA1 and CA3 subregions, and a consequential decline in spatial recognition memory among breast cancer-bearing mice treated with adjuvant chemotherapy." (PMID 39516074, 2024). "We tested two predicted OCN pairs in each cancer type, including NCSTN and DNM1, and NCSTN and OGT in liver cancer; CCNA2 and PTP4A1, and HIF1A and PARP1 in lung cancer; and CCNA2 and PTP4A1, and PLK1 and PTP4A1 in breast cancer." (PMID 31097707, 2019).
dementia (3 papers, 2023 to 2025). Loss of intellectual abilities interfering with an individual's social and occupational functions. "Dynamin-1 (DNM1), a protein maximally expressed in the central nervous system, plays a pivotal role in memory formation by facilitating effective neurotransmission and synaptic plasticity, and lower DNM1 concentrations have been observed in post-mortem brains of dementia patients." (PMID 39516074, 2024).
Dystonia (3 papers, 2017 to 2025). An abnormally increased muscular tone that causes fixed abnormal postures. "The mutation in the GTPase domain of DNM1 alone could account for moderate neurodevelopmental delay, epileptic seizures, and dystonia (see Video part 1)." (PMID 40717768, 2025).
microcephaly (3 papers, 2021 to 2023). A congenital or acquired developmental disorder in which the circumference of the head is smaller than normal for the person's age and sex. "Pathogenic variants in DNM1 have also been reported in association with other clinical phenotypes such as hypotonia, movement disorder, ASD, cortical visual impairment, and microcephaly." (PMID 37805537, 2023).
Ataxia (2 papers, 2010 to 2025). Ataxia refers to impaired coordination of voluntary muscle movement. "Mice heterozygous for a novel spontaneous Dnm1 mutation—fitful—experience recurrent seizures, and homozygotes have more debilitating, often lethal seizures in addition to severe ataxia and neurosensory deficits." (PMID 20700442, 2010).
autism spectrum disorder (2 papers, 2017 to 2023). A spectrum of developmental disorders that includes autism, and Asperger syndrome. "Further, mutations in some of the genes have been associated with neurological phenotypes, such as Aicardi-Goutierès syndrome (RNASEH2C), intellectual disabilities and epilepsy (DNM1), and autism spectrum disorder (ARRB2)." (PMID 37147306, 2023).
centronuclear myopathy (2 papers, 2013 to 2023). Centronuclear myopathy (CNM) is an inherited neuromuscular disorder characterized by clinical features of a congenital myopathy and centrally placed nuclei on muscle biopsy. "Interestingly, three Vps1 mutants, I277G, G397R, and I442G, corresponding to DNM1 V235G, DNM2 G358R, and DNM2 V375G mutations found in microcytic anemia, Charcot-Marie-Tooth, and centronuclear myopathy, respectively, showed a defect in autophagic flux." (PMID 37060997, 2023).
Cognitive impairment (2 papers, 2010 to 2024). Abnormal cognition is characterized by deficits in thinking, reasoning, or remembering. "If cancer- and chemotherapy-induced reduction of DNM1 is truly linked with the long-term neurodegenerative consequences culminating into cognitive impairments, replacement of DNM1 may be another viable therapeutic strategy for ameliorating CRCI." (PMID 39516074, 2024). "Further investigation on how this relationship may differ between subjective and objective cognitive impairment, and across different cancer and treatment types will also help to better contextualize the role of DNM1 in CRCI pathogenesis." (PMID 39516074, 2024). "After receiving cytotoxic treatment, cognitively impaired cancer patients were found to have 46 ​% lower DNM1 levels than those without impairment (P ​= ​0.049)." (PMID 39516074, 2024).
Colon Cancer (2 papers, 2022 to 2024). "In contrast, DNM1 is overexpressed in H295R-PM-Ptc+ cells, as in colon cancer where high DNM1 expression was significantly correlated with perineural and lymphatic invasion and predicted poor prognosis." (PMID 35631574, 2022).
Dravet syndrome (2 papers, 2024).
glioblastoma (2 papers, 2019 to 2021). The most malignant astrocytic tumor (WHO grade IV). "We validated the regional expression of PLP1 and DNM1 by analyzing their RNA expression in the Ivy Glioblastoma Atlas Project database." (PMID 32642662, 2019).
kidney failure (2 papers, 2017 to 2022). An acute or chronic condition that is characterized by the inability of the kidneys to adequately filter the blood. "Our studies showed that loss of both Dnm1 and Dnm2 specifically in mouse podocytes (Dnm-DKO) exhibited massive proteinuria, progressive glomerulosclerosis, and kidney failure." (PMID 35223901, 2022).
lung carcinoma (2 papers, 2019 to 2024). "DNM1 is overexpressed in many lung cancers, enhances the growth, migration, and invasion of cancer cells, and reduces the survival rate of lung cancer patients." (PMID 38167056, 2024).
melanoma (2 papers, 2017 to 2025). A malignant, usually aggressive tumor composed of atypical, neoplastic melanocytes. "Among these, VSNL1, ATP6V1G2, and DNM1 exhibited significant downregulation in both PD patients and melanoma patients, suggests a common molecular mechanism underlying these two conditions." (PMID 40066251, 2025). "Retinoic acid was found to have binding affinity for VSNL1, ATP6V1G2, and DNM1, indicating its potential as a therapeutic agent for PD and melanoma." (PMID 40066251, 2025). "A total of 41 overlapping DEGs were identified, including VSNL1, ATP6V1G2, and DNM1, which were significantly down-regulated in both PD and melanoma patients." (PMID 40066251, 2025). "In the quest for potential anti-PD and anti-melanoma medications, drugs capable of targeting VSNL1, ATP6V1G2, and DNM1 were identified through screening in the DsigDB database." (PMID 40066251, 2025). "The transcripts of 6 significantly changed proteins (VIM, DNM1, SMARCC2, CSDE1, EIF4A2 and ANXA2) have been previously identified as direct RNA targets of CSDE1 in human melanoma cells." (PMID 29129916, 2017).
viral infection (2 papers, 2016 to 2024). "The data demonstrated that Dnm1, Dnm2, and Dnm3 had significant effects on virus infection in shrimp." (PMID 27029712, 2016). "Given that Dnm1, Dnm2, and Dnm3 could be involved in virus infection at the mRNA level, we further hypothesized whether or not recombined Dnm1, Dnm2, and Dnm3 proteins affect the WSSV copies in shrimp." (PMID 27029712, 2016).
acute myeloid leukemia (1 paper, 2024). Acute myeloid leukemia (AML) is a group of neoplasms arising from precursor cells committed to the myeloid cell-line differentiation. "GSEA analysis showed that genes related to DNM1 in the training set were mainly enriched in aminoacyl tRNA biosynthesis, acute myeloid leukemia and other pathways." (PMID 38167056, 2024).